CXCR4 (C-X-C motif chemokine receptor 4)
Diseases named in the same sentence as CXCR4 in open-access papers (continued):
Sharing a sentence is not in itself a finding about the gene and the disease.
melanoma (continued). "A growing body of evidence indicates that the CXCR4 inhibitor X4-136 inhibits the growth of murine B16/OVA melanoma tumors, diminishes immune-regulatory cell populations in the melanoma microenvironment, and also impairs the growth of renal cell carcinoma in Renca-DM syngeneic models." (PMID 37460927, 2023). "Furthermore, 4 melanoma pathway genes (CDKN1A, CDKN2A, CXCR4 and RAD51) were also expressed differently in normal tissues compared with melanoma." (PMID 38070141, 2023). "Furthermore, CDKN1A, CDKN2A, CXCR4 and RAD51 in the melanoma pathway, were also differentially expressed between normal skin and melanoma." (PMID 38070141, 2023). "One hundred and thirty-eight clinical trials with CXCR4 inhibitors are being/have been performed, none of which include(d) melanoma." (PMID 35158973, 2022). "The effect of targeting CXCR4 on the TME is also currently being investigated in renal cell carcinoma, Waldenström macroglobulinaemia, and melanoma, upon combined treatment with the allosteric CXCR4 modulator Mavorixafor and anti-PD1 immune checkpoint blockade (ClinicalTrials.gov: NCT04274738)." (PMID 35159113, 2022). "Additionally, we found that USMB-shMincle significantly inhibited CXCR4 and MMP-13 expression in both human melanoma and lung cancer mouse models." (PMID 34589582, 2021). "Yang and colleagues found that knocking down only YTHDF2 significantly increased the mRNA stability of PD-1 (PDCD1), CXCR4, and SOX10; in conjunction, the proliferative and migratory capacities of the melanoma cells were increased (in vitro) as was tumor growth (in vivo)." (PMID 34105069, 2021). "A combination of the CXCR4 antagonist X4P‐001 in combination with Pembrolizumab reactivating CD8 TIL demonstrated a clinical response in patients with advanced melanoma (phase 1b trial, NCT02823405)." (PMID 33988305, 2021). "Notably, the bone tropism can also be attained by melanoma-derived exosomes, which are able to induce the CXCL12/CXCR4 axis." (PMID 33238004, 2020). "Additionally, ADM3100, a specific antagonist of the CXCR4/CXCL12 pathway, decreases the accumulation of TAMs and prevents B16 melanoma progression in mice." (PMID 33224886, 2020). "In addition, the human specific CXCR4 antagonist, Pep R54, cooperated with nivolumab in inhibiting the growth of the PD-1 expressing human PES43 melanoma xenograft." (PMID 31661001, 2019). "The machinery driving the colonization by melanoma cells of metastatic sites, including the bone, has been poorly investigated although previous studies correlated the CXCR3, CXCR4, CCR7 and CCR10 expression with the enhanced propensity to migrate to lymph nodes, lung and skin." (PMID 31324252, 2019). "The chemokine receptor subtype-4 (CXCR4) is an interesting new target for TRT, as it is overexpressed in more than 70% of human solid tumours, including breast, prostate, and cervical cancers and B-cell lymphoma, neuroblastoma, melanoma and gliomas." (PMID 30823564, 2019). "Since FTO promotes melanoma tumorigenicity and regulates the expression of tumor-promoting melanoma cell-intrinsic PD-1 as well as CXCR4 and SOX10, we reasoned that FTO may also regulate the response of melanoma to immunotherapy." (PMID 31239444, 2019). "Furthermore, we found that overexpression of PD-1 (PDCD1), CXCR4, or SOX10 inhibited IFNγ-induced cell death in FTO-knockdown melanoma cells." (PMID 31239444, 2019). "In addition, by silencing the CXCR4 receptor we also demonstrated that CXCR4 and CXCR7 co-expression by melanoma cells drive their SDF-1-mediated chemotaxis independently from Exo stimulation." (PMID 31324252, 2019). "In contrast, SDF-1 overexpression by melanoma cells in the B16-ova melanoma model has been shown to chemo-repel antigen-specific cytotoxic T cells suggesting a complex and fine-tuned control of Teff infiltration by SDF-1/CXCR4 signaling." (PMID 30622535, 2018).
melanoma (continued). "Incorporation of Cox-2 and CXCR-4 promoters in adenovirus genome has been shown to significantly enhance the virus-mediated gene expression in the malignant melanoma instead of non-malignant primary melanocytes." (PMID 28567163, 2017). "The B16.F10 melanoma cells used in our experimental model did not express CXCL12 or CXCR4, ruling out direct effects on melanoma cells." (PMID 27590504, 2016). "In this study we have analyzed, using flow cytometry, the systems formed by the chemokine receptors CXCR3, CXCR4, CXCR7, CCR7 and CCR10 and their ligands in thirteen human melanoma cell lines (five established from primary tumors and eight established from metastasis from different tissues)." (PMID 24559071, 2014). "Although CXCR4 expression is low or absent in normal tissues, CXCR4 is overexpressed in many cancer types, including melanoma, breast, ovarian, prostate and colorectal cancers." (PMID 24629239, 2014). "Early studies have suggested a role for CXCR4 in experimental LN metastasis in a murine breast cancer model, but not in a melanoma metastasis model in mice." (PMID 24212647, 2011). "The CXCR4 gene promoter had no required specificity; its activity in the normal melanocytes was even higher than in melanoma cells." (PMID 22649681, 2011). "CXCR4 and CCL20 expression has been described in a variety of human neoplasms, including colorectal, lung, pancreatic and breast human adenocarcinomas, malignant glioma, leukemia, lymphoma and melanoma as well as by normal keratinocytes." (PMID 19340288, 2009). "In neural crest, melanocyte, and melanoma cells, PAX3 was found to regulate MITF, NGN2, RET, SOSTDC1, MSX2, DCT, and TYRP1 genes, as well as genes expressed ubiquitously or widely (and including melanocytes), such as BCL-XL, CXCR4, FGFR4, HES1, MET, NF1, TGFb2, and WNT1." (PMID 40428399, 2025). "However, the interplay between CXCR4 and RUNX2 in melanoma cells remains poorly understood." (PMID 38474372, 2024). "Possible future steps could be the quantification of CXCR4 and markers of cell invasiveness, autophagy, and mTOR signalling, in biopsies from metastatic and non-metastatic melanoma patients, by immunohistochemistry." (PMID 38474372, 2024). "Immunohistochemical staining confirmed these findings showing high GLUT1 (C) and low CXCR4 expression (D) in an osteolytic melanoma lesion (arrows; SUVmax 14.0 vs. 2.2) as opposed to intense CXCR4 expression (E) in a site with osseous CLL infiltration (dotted arrows; SUVmax 2.6 vs. 9.1)." (PMID 39008062, 2024). "In addition, CXCR4 and SOX10 are critical melanoma-promoting genes." (PMID 31239444, 2019). "In addition, herein increased expression of stem cells and metastasis related markers CD133, nestin, CXCR4, and NGF-R along with continued high-level of CD10 expression were observed, which usually delineates progression to advanced stage of melanoma and metastatic tumour formation." (PMID 28125999, 2017). "Circulating pDCs from patients with melanoma have been found to express higher amounts of CCR6 and CXCR4, while their corresponding ligands CCL20 and CXCL12 are expressed on melanoma cells, suggesting that the CCR6/CCL20 and CXCR4/CXCL12 axes promote pDC migration from blood to melanoma foci." (PMID 29085361, 2017). "Framycetin, a CXCR4 inhibitor, has not previously been considered for melanoma treatment." (PMID 37133296, 2017). "Other studies supported the idea that the CXCR4/CXCL12 axis is the principle mechanism for marrow homing of normal or malignant cells and may therefore regulate migration and metastasis of a variety of cancer types including melanoma and colon cancer." (PMID 22433180, 2012). "Regarding chemokine receptors, FGFR Mut melanoma expressed higher levels of CCR5, CCR7, CXCR3, CXCR4 and CXCR6 than their wild-type counterparts, but no statistical difference was observed (all P > 0.05)." (PMID 36426352, 2022).
melanoma (continued). "Immunohistochemical analysis of chemokine receptor expression patterns in non-melanoma skin cancer demonstrated downregulation of CCR6 and upregulation of CCR7 and CXCR4 in potentially metastatic non-melanoma skin cancer." (PMID 35203305, 2022). "CXCR4 is the most widely expressed chemokine receptor among more than 23 human cancers, including breast, ovary, melanoma, prostate, and CRC, though CXCR4 expression is low or absent in many normal tissues." (PMID 34298991, 2021). "Specific CXCR4 binding was obtained in cells overexpressing human CXCR4 (B16-hCXCR4 and human melanoma cells PES43), but not in CXCR4 low expressing cells (FB-1)." (PMID 28566721, 2017). "Consistent with this, we found that both CXCR4 and MIR21 were upregulated in metastatic compared to non-metastatic primary melanomas." (PMID 26918341, 2016). "The lack of influence of CXCR4 in ovarian cancer could reflect the peculiar characteristics of the metastatic process in ovarian cancer as compared to other cancers such as colon, non-small-cell lung cancer, gliomas, malignant melanomas, oral squamous carcinoma, and adult acute myeloid leukemia." (PMID 20049170, 2010). "Interestingly, in vitro studies with different melanoma cell lines suggest that osteotropic melanoma-derived sEVs induce CXCR7 expression in non-osteotropic cells and promote the SDF-1/CXCR4/CXCR7 axis." (PMID 36704194, 2022). "We could not establish that the sensitivity of individual melanoma cell lines to MIF depletion resulted from the differential expression of known MIF receptors (i.e. CD74/CD44 and/or CXCR4)." (PMID 25168062, 2014).
leukemia (225 papers, 2009 to 2025). A malignant (clonal) hematologic disorder, involving hematopoietic stem cells and characterized by the presence of primitive or atypical myeloid or lymphoid cells in the bone marrow and the blood. "Treatment methods include targeting the chemokine receptors, notably CXCR4, which are linked to leukemia cell proliferation and drug resistance (SDF1-CXCR4 axis)." (PMID 40114928, 2025). "Taking advantage of flow cytometry combined with high dimensional analysis, we observed a distinctive cluster of cells that are CD10+CD19+CXCR4+sGRP78+ (cluster 2) associated with pediatric High-risk leukemia at diagnosis." (PMID 35149705, 2022). "We confirmed that sGRP78+CXCR4+ blood-derived cells were more frequent in High-risk leukemia patients." (PMID 35149705, 2022). "Clusters 1–4 contained Dx cells that were enriched for CXCL8 and CXCR4, genes associated with the interaction between leukemia blasts and stromal cells." (PMID 35986270, 2022). "The prognostic value of CXCL12/CXCR4 axis in leukemia has been studied to push forward risk-stratified therapeutic strategies." (PMID 34246314, 2021). "Loss of CXCR4 decreased leukemia initiating cell activity in vivo and modulated targeted key T-ALL regulators, such as the MYC pathway." (PMID 34026651, 2021). "Taken together, these findings suggest that loss of CXCR4 in leukemia cells leads to increased oxidative stress, differentiation, and activation of p38 and NF-κB signaling." (PMID 32460032, 2020). "Our data suggest that loss of CXCR4 expression leads to development of leukemia cells that have elevated NF-κB signaling, probably reflecting a more differentiated state of the cells rather than NF-κB signaling driving the differentiation effect itself." (PMID 32460032, 2020). "CXCR4 expression levels in CD34+ leukemia cells are associated with poor survival and higher probability of relapse in AML patients." (PMID 32754595, 2020). "Signals from the CXCL12-chemokine receptor 4 (CXCR4) axis have been shown to act as critical mediators in interactions between leukemia cells and the microenvironment, which are the major cause of chemotherapy resistance and disease relapse in AML11,12." (PMID 31434952, 2019). "A significantly higher CXCR4 RFI was detected on the surface of leukemia cells in the FLT3-ITD mutated AML group (9.24 ± 5.51, mean ± SD) than in the FLT3-wt group (5.72 ± 4.44, P ≤ 0.0001)." (PMID 31434952, 2019). "The results showed that the level of CXCR4 expression was related to the presence of FLT3‐ITD mutations in leukemia blasts." (PMID 31518054, 2019). "CXCR4 is overexpressed in more than 23 human cancers including leukemia, is associated with metastasation, and has been identified as a marker for poor prognosis in human patients." (PMID 29951060, 2018). "We found that primary leukemia cells from CLL patients have significantly higher levels of CXCR4 expression compared with normal B cells and that high-risk prognostic factors do not influence the level of expression of this chemokine receptor." (PMID 26646452, 2016). "In addition, elevated CXCR4 expression on leukemia cells were also found to be associated with a poor prognosis in patients with AML." (PMID 39871937, 2024). "Testing the presence of sGRP78 and CXCR4 together with conventional markers may help to achieve a better categorization of High and Standard-risk pediatric leukemia at diagnosis." (PMID 35149705, 2022). "Since we observed the presence of sGRP78+CXCR4+ double positive cells in high-risk leukemia samples, both in bone marrow and peripheral blood, we wondered whether purified sGRP78+ cells could be ready to migrate and disseminate." (PMID 35149705, 2022). "Similarly, we also observed that High-risk leukemia patients had a higher proportion of sGRP78+ CXCR4+ cells." (PMID 35149705, 2022).
leukemia (continued). "Since CXCR4 has been implicated in homing of leukemia cells to their niche, we tested the effect of plerixafor (AMD3100) in the colonization of AMD3100-treated B-ALL cells to the 3D structures and found that it can only partially prevent B-ALL cell spheroid colonizing, with a 4.6-fold decrease." (PMID 34737747, 2021). "Moreover, expression of mutated Cxcr4 variants reveals that CXCR4 signaling is essential for leukemia cells." (PMID 32460032, 2020). "Notably, loss of CXCR4 signaling in leukemia cells leads to oxidative stress and differentiation in vivo." (PMID 32460032, 2020). "Along these lines, it has recently been shown that calcineurin (a serine/threonine protein phosphatase) previously associated with leukemia initiating cell activity, affects CXCR4 cell-surface expression at least partially through increased cortactin expression and thus CXCR4 recycling." (PMID 29666622, 2018). "Notably, CXCR4 is the most extensively studied chemokine receptor in malignant hematologic diseases, being closely associated with malignant proliferation, apoptosis regulation, chemotherapy resistance, and the bone marrow microenvironment of leukemia cells." (PMID 40427609, 2025). "Interestingly, though the proportions of sGRP78+ cells coexpressing CD34, CD38, CD10 or CXCR4 were significantly higher in High-risk leukemia population, these samples showed the presence of a subgroup of double positive cells rather than a general increase of the positivity to the analyzed markers." (PMID 35149705, 2022). "Since NFAT-deficient cells also present reduced CXCR4 cell surface expression level, this defect could explain the migration default and impaired leukemia inducing potential as demonstrated for Cn-deficient leukemic cells, reinforcing a major role for Cn/NFAT axis in T-ALL." (PMID 34234374, 2021). "Therefore, we speculated that FLT3-ITD mutations potentiallyupregulate CXCR4 expression on the surface of leukemia cells and enhance the chemotaxis of AML cells toward CXCL12, consistent with previously reported results." (PMID 31434952, 2019). "A study indicated that drug-resistant leukemia strains remain unaffected by CXCR4 antagonists, whereas primary leukemia cells localize in bone marrow niches via surface CXCR4/CXCL12 interactions." (PMID 40427609, 2025). "This construct diminishes the infiltration of leukemia cells in the spleen by augmenting the specific apoptotic effects of KLA peptides in CXCR4-positive leukemia cells, consequently decelerating disease progression and improving overall survival." (PMID 40496863, 2025). "Previous studies found that the interaction between leukemia cells and the bone marrow hematopoietic microenvironment is a critical cause of chemotherapy resistance and disease recurrence, with the CXCL12/CXCR4 axis playing a pivotal role in this interaction." (PMID 40427609, 2025). "Application of CXCR4 inhibitor AMD3100 or targeting down-regulation of integrin β1 can weaken the promoting effect of MSCs with CAFs phenotype on leukemia cell migration and invasion." (PMID 40626005, 2025). "This highlights the potential value of CXCR4 antagonists as chemical sensitizers in preconditioning regimens and immune sensitizers for graft-versus-leukemia effects in allogeneic hematopoietic stem cell transplantation." (PMID 40427609, 2025). "Among these, the chemokine CXCL12 and its receptor CXCR4 are crucial for mediating interactions between leukemia cells and their microenvironment, promoting cell migration and survival, thereby contributing to chemotherapy resistance." (PMID 40608798, 2025). "The expression and activity of CXCR4 are associated with tumor cell invasion, proliferation, migration, and the tumor microenvironment; blocking CXCR4 mobilizes leukemia cells from the bone marrow microenvironment." (PMID 40308758, 2025).